KRAS (KRas proto-oncogene, GTPase)
Diseases named in the same sentence as KRAS in open-access papers (continued):
Sharing a sentence is not in itself a finding about the gene and the disease.
tumor (continued). "Thirty-one tumors presented concomitant mutations in two genes; three tumors presented concomitant mutations in three genes including one tumor with BRAF, NRAS and PIK3CA concomitant mutations and two tumors with BRAF, KRAS, and PIK3CA concomitant mutations." (PMID 31036005, 2019). "Tumor molecular profiling was retrieved from clinical documentation when available: 62% (n = 44/71) were KRAS mutant, 3% (n = 2/58) NRAS mutant, 4% (n = 3/68) BRAF mutant and 20% (n = 6/30) HER2 amplified." (PMID 31355139, 2019). "As demonstrated through immunohistochemistry, the positive expression of the KRAS oncoprotein in the cytoplasm of tumor cells was relatively weak in the tumors derived from the RC‐ODC/AZ group." (PMID 30347501, 2019). "Unsupervised hierarchical clustering of tumor samples evidenced two clusters, which were found to be differently enriched in KRAS-mutant samples." (PMID 31405063, 2019). "We then profiled immune cells in KRAS* tumor at 9 days after IRE treatment, at which time 5 doses of anti-PD1 had been injected for the anti-PD1 and combination groups." (PMID 30796212, 2019). "These circuits often restore critical functions of KRAS*, such as tumor cell proliferation and evasion of apoptosis, thereby enabling cancer cells to escape KRAS* withdrawal." (PMID 31134896, 2019). "This growing body of knowledge points to the complexity of this system and suggests that analysis of the genetic context and the metabolic activity of the tumor should be combined to identify KRAS-driven metabolic vulnerabilities and stratify patients." (PMID 31544066, 2019). "In malignant KRAS-driven tumor cells, autophagy helped to reverse low asparagine-induced metabolic barriers and thus permitted tumor invasion." (PMID 31681605, 2019). "The expression of CXCL1, CXCL2, CXCL5, and CXCL8, which are CXCR2 ligands, and the expression of KITL and GM-CSF are strongly enhanced by KRAS signaling in cancer cells and tumor-derived hypoxia." (PMID 31474975, 2019). "Excitingly, the exosomes targeting KRAS suppressed tumor development and significantly increased mouse overall survival." (PMID 30961650, 2019). "Although KRAS mutations are a major driver of PDA, CEACAM6 KO in KRAS mutant PDA cells severely compromised tumor growth." (PMID 31797958, 2019). "For the 17 mCRC patients who received zFOLFIRI after prior bevacizumab plus FOLFIRI, 13 had mutant tumor KRAS, 3 had WT KRAS, and one had BRAF V600E." (PMID 30923702, 2019). "In this study, we found that RAF inhibitor (AZ628) combined with STAT3 inhibitor (BP-1-102) reversed this little efficacy, and had a great effect on suppressing the growth of KRAS mutant cancer cells and tumor." (PMID 31484165, 2019). "Mutant KRAS is well established as a true oncogenic driver – it is sufficient for neoplastic transformation in vitro, induces spontaneous tumor formation in genetically-engineered mouse models, and its expression is strictly required, even in advanced tumors." (PMID 31413817, 2019). "Tumor vascularization is further driven by KRAS-mediated induction of hypoxic HIF signaling, which drives expression of vascular endothelial growth factor (VEGF)." (PMID 31681559, 2019). "On the other hand, some studies reported that mutant KRAS ctDNA or total cfDNA were statistically irrelevant with respect to tumor staging." (PMID 31850201, 2019).
tumor (continued). "Even more interestingly, we identified a few patients considered KRAS wild-type by tumor tissue sequencing that had significant KRAS mutant levels in their blood." (PMID 31142037, 2019). "His tumor was KRAS wild-type based on tissue analysis and he was treated sequentially with cetuximab-based chemotherapy, chemotherapy alone and panitumumab-based chemotherapy." (PMID 30967998, 2019). "Studies on American CRC populations have indicated that CIMP is significantly associated with female sex, older age, proximal tumour location, MSI, BRAF mutation, and wild-type KRAS." (PMID 31690257, 2019). "Mutant KRAS expression promotes oncogenic transformation and downregulation of mutant KRAS leads to tumor regression." (PMID 31189880, 2019). "Two separate KRAS driven murine tumor cell lines (KPC-1 and CT26) were treated with KRAS-siRNA NP in vitro for 24 hours." (PMID 31413817, 2019). "Sustained KRAS* pathway suppression in the iKRAS model was shown to induce significant tumor regression; however, this was often followed by rapid tumor re-growth." (PMID 31134896, 2019). "The metabolic changes are closely linked to signaling triggered by activation of oncogenes like KRAS as well as inactivation of tumor suppressors." (PMID 31832601, 2019). "Tumor tissues were also analyzed by western blot for the effects of miR-873 delivery on KRAS expression." (PMID 30654191, 2019). "Let-7 suppresses lung tumor via KRAS in vivo, and exogenous lentivirus-mediated let-7 delivery significantly reduces the tumor burden in mouse models of NSCLC." (PMID 30813457, 2019). "Oncogenic mutants of KRAS, such as the prevalent KRASG12D mutation, have transforming activity and are thought to be founder mutations as they can initiate and drive tumour progression in mouse models." (PMID 30760495, 2019). "Tumor size measurement at the end of the treatments revealed that delivery of anti-miR-21, as well as si-KRAS, significantly reduced mPDAC tumor growth by 37.3% and 37.6% respectively." (PMID 31523393, 2019). "AC009 also reduced cancer stem-cell marker CD44+/CD24+ expression and restored the tumor inhibition effect of cetuximab in KRAS-mutant CRC." (PMID 31717759, 2019). "In order to identify possible mechanisms of resistance to anti-EGFR MoAbs in CRC, we analyzed tumor samples from 21 KRAS/NRAS/BRAF/PIK3CA wt mCRC patients enrolled in the CAPRI-GOIM clinical trial by targeted sequencing." (PMID 31226844, 2019). "They found an enrichment of tumours with HER2 amplification in cetuximab‐resistant KRAS/NRAS/BRAF/PIK3CA wild‐type tumours." (PMID 31282586, 2019). "To assess the combined survival effect of the tumor tissue mRNA expression of 27 cytokines and variables, such as the clinicopathological parameters and the EGFR/KRAS mutation state, we applied multivariate survival analysis." (PMID 31004093, 2019). "Orthotopic injection of 1×107 KRAS-shTp53-shCdkn2a/b lentiviral particles into the head of the pancreas induced tumor formation with full penetrance after 3-7 weeks." (PMID 30910991, 2019). "SiG12D-LODER is a biodegradable implant for the local delivery of liposomal-encapsulated anti-KRAS siRNA that is placed near the tumor by means of standard endoscopic surgery." (PMID 31824928, 2019). "This is in contrast to faster tumor growth of KRAS knockout mutant of ~35% growth suppression vs. KRAS mutant cells." (PMID 31797958, 2019). "It is known that MEK inhibitors, such as AZD6244 and trametinib, have been developed in clinical studies in cancer, and have the potential to suppress KRAS mutant tumor rely on MAPK signaling pathway." (PMID 31484165, 2019). "In summary, mutant KRAS seems to influence the composition of the immune microenvironment through a multitude of mechanisms that are definitely context and tumor-type dependent." (PMID 31847096, 2019).
tumor (continued). "Downstream to SHP-2, MAPK and PI3K/AKT pathways are also potential targets for neoplasms with mutated PTPN11 and KRAS, and for which several FDA-approved inhibitors are currently available." (PMID 31277422, 2019). "These two SNPs are located in the 3’ untranslated region (UTR) of KRAS, where they disrupt a let-7 miRNA binding site, thus increasing KRAS expression and enhancing tumor growth." (PMID 30860980, 2019). "AZD4785, a potent and selective KRAS therapeutic cEt-ASO, is currently being developed to treat KRAS-dependent tumours." (PMID 30927008, 2019). "Droplet Digital PCR (ddPCR) was performed to detect common point mutations in the KRAS and BRAF oncogenes in cfDNA from 65 patients and compared to mutations in tumor tissue." (PMID 31134762, 2019). "In conclusion, syn-miR-143 exhibited its anti-tumor effect on HER2-positive GC by impairing the KRAS networks systematically, including DDX6 RNA helicase." (PMID 30959742, 2019). "Here we have used a cohort of well-characterized CRC organoids to study the influence of tumor heterogeneity on the activity of the KRAS/MAPK-signaling pathway and the consequences of treatment by inhibitors targeting EGFR and downstream effectors." (PMID 30925167, 2019). "Treatment of KRAS G12D mice with KRA-533 for four months resulted in significant reduction of tumor burden and multiplicity in the lung." (PMID 30971271, 2019). "Our study provides insight into the notion that the presence of mutated KRAS, as well as MSI-H tumor status, are associated with increased formation of TNTs." (PMID 31247990, 2019). "We amplified regions of 192 somatic mutations (including SNVs and INDELs) and the KRAS and GNAS hotspot mutations from DNAs extracted from the corresponding FFPE tumor samples and validated them by deep sequencing and capillary sequencer." (PMID 31225717, 2019). "It is well known that oncogenic KRAS induces glycolysis and recent studies demonstrated that KRAS signaling plays a profound role in the transcription of glucose transporters and key glycolysis genes in tumor cells." (PMID 31569510, 2019). "For instance, KRAS mutation status across 121 patients with NSCLC, melanoma, breast, uterine, pancreatic cancers was compared between cfDNA and matching tumours." (PMID 31817150, 2019). "Activating oncogenic mutations in KRAS and NRAS are common in CRC, driving tumor progression and influencing efficacy of both cytotoxic and targeted therapies." (PMID 31427573, 2019). "The same driven mutations (KRAS G12S in A549, EGFR L858R and T790 M in H1975) were detected in the DNA isolated from LXY30-enriched exosomes and tumor cells by polymerase chain reaction (PCR) and Sanger sequencing." (PMID 31182116, 2019). "We then analyzed the correlation between KRAS MAF in ctDNA or tumor tissue and clinical characteristics of PC patients." (PMID 31850201, 2019). "KRAS mutations have been reported in 30% to 50% of CRC tumors and are also common in other tumor types." (PMID 31126331, 2019). "Of note, GC1118 showed a more significant inhibitory effect on tumor growth than did cetuximab in cases of KRAS-mutant CRC." (PMID 31771279, 2019).
tumor (continued). "One study from 2008 reported similar mutation profiles between surgically collected pancreatic duct juice and tumor tissues from PDAC patients, but only three hotspot KRAS mutations were analyzed." (PMID 30611220, 2019). "Some researchers have found that “KRAS addiction” is associated with EMT (epithelial to mesenchymal transition) and tumor cell survival." (PMID 31867280, 2019). "MRTX849 shows broad-spectrum anti-tumor activity in a panel of patient- and cell-derived in vivo tumor models with KRAS G12C-substitution, with complete tumor regression observed in a subset of these models." (PMID 31612108, 2019). "It is well established that KRAS signaling induces changes in the extracellular matrix that are highly conducive to tumor expansion and metastasis." (PMID 31247990, 2019). "Studies from two different laboratories conjointly established that YAP and TAZ activation drive mutant KRAS-independent tumor growth and progression." (PMID 31109009, 2019). "Having demonstrated that MT KRAS contributes to immunosuppression via a cell-extrinsic mechanism, we next assayed the tumor microenvironment for the increased presence of Tregs using a novel method." (PMID 31635338, 2019). "We also mapped our data with top 20 mutated genes in CRC from COSMIC data sets and found FAT1 and FAT4 to be mutated in tumour, whereas distal margin showed the presence of FAT1, KRAS and SMAD4 mutations." (PMID 30950180, 2019). "In general, mutant KRAS fosters tumor growth by shifting cancer cell metabolism toward anabolic pathways." (PMID 31544066, 2019). "To further test the role of GLI2 in tumor relapse following KRAS* suppression, we grew iKRAS cell lines (iKRAS1 and iKRAS4) in the presence or absence of Dox for 15–18 days following shRNA mediated knockdown of Gli2." (PMID 31134896, 2019). "We investigated a status of KRAS point mutation and its sequence at codon 12 in 51 NSCLC patients after tumor resection." (PMID 30368666, 2019). "Epithelial autophagy: Tumor epithelial autophagy in KRAS-driven cancers alters inflammatory mediators to suppress the immune response." (PMID 31671556, 2019). "Total KRAS expression in the tumor samples varies between 2.0 and 5.7 fmol/3 μg (median 3.0 ± 1.4 fmol/3 μg), and between 0.4 and 1.9 fmol/3 μg (median 1.6 ± 0.6 fmol/3 μg) in the healthy control tissues." (PMID 31805664, 2019). "Genetic mouse models revealed that EGFR deletion attenuates mutant KRAS activity and transiently reduces tumor growth." (PMID 31612108, 2019). "In particular, in a KRAS-mutated NSCLC model, it has been shown that BETi remodel the cancer immune microenvironment, by reducing tumor-infiltrating Treg and inducing T-helper type 1 lymphocytes." (PMID 30841549, 2019). "Koyama and colleagues have deeply investigated the effects of LKB1 on the tumor immune microenvironment studying KRAS/LKB1 mutant (KL) NSCLC mouse models, human samples, and cell lines." (PMID 30995715, 2019). "Our results show that patients can be well separated between KRAS-amplified and KRAS-normal using gene expression in these two tumor types, confirming the presence of a transcriptionally defined subset of patients with KRAS copy number gains." (PMID 31379928, 2019).
tumor (continued). "Tumours manage to survive the ablation of mutant KRAS, despite the development of KRAS-targeted drugs." (PMID 30833665, 2019). "Both GC1118 (TGII = −36.8%, p = 0.0053) and cetuximab (TGII = −29.4%, p = 0.006) induced complete tumor regression in CRC-003T PDXs (KRAS-wild-type; high-affinity ligand, 77.2%; low-affinity ligand, 22.8%) (GC1118 vs. cetuximab, p = 0.09)." (PMID 31771279, 2019). "We propose that B2M testing is a useful adjunct to routine MMR testing and should be incorporated into a bowel tumour‐specific assay in conjunction with MLH1, KRAS, NRAS and BRAF status to provide an overall recurrence risk for individual patients." (PMID 31062389, 2019). "Hence, it is actually unknown if the here analyzed ADAM17 mutations are actively driving tumorigenesis (‘driver mutation’) or if another mutation, e.g., within the oncogene KRAS gene is primarily involved in tumor formation and variants within ADAM17 are found as a so-called ‘passenger mutations’." (PMID 31060243, 2019). "Tumour formation assays showed that trametinib synergized with KRAS knockdown or deltarasin in suppressing tumour growth." (PMID 30833665, 2019). "Aside from KRAS/BRAF mutations, TKIs-treated tumors can gradually generate persistent genetic alterations and allow tumor toleration through compensatory pathways." (PMID 31703359, 2019). "For example, miR-143, which is frequently downregulated in CRC, exerts tumor-suppressive functions by targeting KRAS oncogene expression." (PMID 31717435, 2019). "Objective regression was observed of lung metastasis after the infusion of HLA-C*8:02-restricted tumor infiltrating lymphocytes that were composed of four different T cell clonotypes that specifically targeted KRAS G12D." (PMID 35582274, 2019). "Since it is difficult to obtain sufficient or appropriate tumor samples for KRAS genotyping, an alternative method is required." (PMID 31877940, 2019). "Based on our results, wild-type EGFR is important for proliferation and migration of KRAS-mutant tumor cells." (PMID 30935067, 2019). "Mutant KRAS has important functions in influencing a variety of malignant characteristics of tumor cells." (PMID 30347501, 2019). "Among the most frequently altered metabolic regulators were PTEN (in 14% of all tumours), KRAS (in 11%) and MYC (in 11%)." (PMID 31754644, 2019). "KRAS and NRAS tumour mutational status are required for anti-EGFR mAbs prescription since the presence of mutations in exons 2, 3 or 4 of these genes have extensively been described as predictive marker of treatment resistance." (PMID 31265477, 2019). "Co-occurring genetic mutations, which can lead to differential downstream effectors engaged by mutant KRAS, have been reported to significantly affect the tumor immune signatures and responses to immunotherapy." (PMID 31612108, 2019). "SOC FFPE KRAS testing results on primary tumor specimens were only available for 43 KRAS-MUT+ patients with MAF values < 1% at the hospital centers performing OncoBEAM testing." (PMID 31222012, 2019). "KRAS and EGFR mutations are usually mutually exclusive but when they coexist, mainly in tumours under EGFR-TKIs treatment, KRAS mutations can confer resistance to EGFR inhibitors." (PMID 31795465, 2019). "Advances in ASO chemistry have enabled the generation of therapeutic ASOs with drug-like properties including AZD4785, a potent and selective KRAS ASO that is being developed to treat KRas-dependent tumours." (PMID 30927008, 2019). "Co-immunofluorescence staining of blood vessels with CD31 showed that FITC-dextran extravasated into the interstitial space of KRAS* tumor at 4 days after IRE." (PMID 30796212, 2019).